ACLY (ATP citrate lyase)
Diseases named in the same sentence as ACLY in open-access papers (continued):
Sharing a sentence is not in itself a finding about the gene and the disease.
glioblastoma (21 papers, 2015 to 2025). The most malignant astrocytic tumor (WHO grade IV). "In glioblastoma cells, increased ATP citrate lyase (ACLY) dependent acetyl-CoA levels caused increased histone 3 acetylation specifically at the genes promoting adhesion and migration." (PMID 33923766, 2021). "ACLY has been implicated in integrin signaling in glioblastoma leading to cell adhesion and migration required for its progression and metastasis." (PMID 30717356, 2019). "For de novo fatty acid synthesis, glioblastoma cellsmust produce cytosolic acetyl-CoA, which can be generatedeither from citrate via ATP-citrate lyase or from acetate viaacetyl-CoA synthetase (Santos, Schulze, 2012)." (PMID 39944803, 2024). "It has been shown that ACLY promotes cell migration in glioblastoma through mechanisms involving histone modification." (PMID 39251875, 2024). "These ACLY KO pancreatic cancer cells showed little to no reliance on exogenous acetate for proliferation, which is similar to that previously observed in ACLY null glioblastoma cells." (PMID 37134161, 2023). "Inhibition of ACLY inhibits glucose-dependent histone acetylation to suppress glioblastoma cell proliferation." (PMID 31828117, 2019). "Similarly, in glioblastoma, ACLY accumulation in pseudopodia sustains migration and preserves glycolytic flux under mitochondrial inhibition." (PMID 41411367, 2025). "In contrast, FABP7wt overexpression increased level of acetyl‐CoA in nuclei and ACLY activity, indicating nuclear localization of FABP7 in glioblastoma may be essential for the production of nuclear acetyl‐CoA through the interaction with nuclear ACLY." (PMID 34716958, 2022). "Targeting key lipid metabolism enzymes (SCD, FADS2, ACLY, and ACSL) to re-sensitize cancer cells to chemotherapy has already been demonstrated as a successful approach to combat glioma and glioblastoma." (PMID 38609948, 2024). "In turn, ATP-citrate synthase (ACLY) is O-GlcNAcylated, and CoA production is elevated, resulting in more robust fatty acid levels and histone H3 acetylation for gene transcription in glioblastoma." (PMID 41005476, 2025). "In glioblastoma, fluctuations in acetyl-CoA levels have been shown to regulate H3K27 acetylation at specific genomic loci, with ATP citrate lyase (ACLY)-dependent acetyl-CoA production driving oncogenic gene expression programs involved in cell adhesion and migration." (PMID 41008904, 2025). "Interestingly, we also observed overexpression of ATP-citrate lyase (ACLY) in OPM-BMG tumor xenografts, an established positive regulator of glycolysis in glioblastoma suggestive of increased fatty acid biosynthesis." (PMID 36591481, 2022). "Previously, ACLY-dependent acetyl-CoA production was shown to promote cell migration and extracellular matrix (ECM) adhesion phenotypes that contribute to the invasiveness of glioblastoma multiforme (GBM) tumor cells." (PMID 34573442, 2021).
colon cancer (20 papers, 2019 to 2025). "To evaluate the role of ACLY in colon cancer metastasis, we performed cell migration and invasion assays in two ACLY-deficient colon cancer cell lines." (PMID 31511060, 2019). "Furthermore, a significant upregulation of ACLY expression has been associated with several tumors, including lung, prostate, bladder, breast, liver, stomach, and colon tumors." (PMID 34048454, 2021). "Furthermore, deficiency of ACLY results in changes of epithelial and mesenchymal markers in colon cancer cell lines and nude mouse tissue samples, as EMT is a crucial step in the invasion metastasis process." (PMID 31511060, 2019). "This dependence of ACLY expression from ΔNp63 has also been previously reported in colon cancer stem cells." (PMID 39543093, 2024). "In many tumors such as lung, prostate, bladder, breast, and colon cancers, ACLY is pathologically overexpressed or has enhanced enzymatic activity." (PMID 36425653, 2022). "ACLY can be also involved in the vivo metastasis of colon cancer, promoting the migration and invasion of colon cancer cells." (PMID 35743814, 2022). "Overexpression of ACLY in HT29 colon cancer induced resistance to SN-38, an active metabolite of irrinothecan." (PMID 34829834, 2021). "Overexpression of ACLY has been reported in breast, prostate, bladder, lung, stomach, liver and colon cancers." (PMID 31511060, 2019). "ATP-citrate lyase (ACLY), the first-step rate-controlling enzyme in lipid synthesis, is elevated in colon cancer." (PMID 31511060, 2019). "To further investigate the effects of ACLY deficiency on colon cancer metastasis, we applied the CRISPR Cas9 technology to knock out endogenous ACLY gene in HCT116 cells (KO), and we also obtained RKO cells that stably knocked down ACLY (shACLY) by shRNA-ACLY." (PMID 31511060, 2019). "Firstly, we analyzed the endogenous protein and mRNA levels of ACLY in six human colon cancer cell lines." (PMID 31511060, 2019). "Immunohistochemical analysis of 78 colon cancer patients showed that the high expression levels of ACLY and CTNNB1 protein was positively correlated with metastasis of colon cancer." (PMID 31511060, 2019). "Here, we observe that higher expression level of ACLY in colon cancer cells corresponds with superior migration capability." (PMID 31511060, 2019). "HCT116, RKO and SW480, expressing higher levels of ACLY, were chosen to investigate the significance of ACLY in the process of colon cancer metastasis by the wound healing assay and Transwell invasion assay." (PMID 31511060, 2019). "ACLY has been shown to promote colon cancer metastasis by enhancing EMT." (PMID 41411367, 2025). "OA induced the phosphorylation of ACLY in the KRas-driven colon cancer cell line HCT116 at S455." (PMID 36269753, 2022). "Furthermore, we describe the mechanism of ACLY in promoting colon cancer metastasis in vitro and in vivo." (PMID 31511060, 2019). "Interestingly, we found that ACLY was positively related to CTNNB1 in colon cancer tissues (r = 0.5871, P < 0.001)." (PMID 31511060, 2019). "Some CTNNB1 target genes were differently regulated by ACLY in different colon cancer cells." (PMID 31511060, 2019). "Colon cancer mouse model is used to examine ACLY’s effects on colon metastasis potentials in vivo." (PMID 31511060, 2019). "In this study, we observed that ACLY contributed to colon cancer metastasis in vitro and in vivo." (PMID 31511060, 2019). "Moreover, we found that knockdown of CTNNB1 weakened the effects of ACLY on colon cancer cell migration and invasion." (PMID 31511060, 2019). "However, it remains unclear about the exact role of ACLY in the development of colon cancer metastasis." (PMID 31511060, 2019). "Furthermore, we found that ACLY promoted migration and invasion of colon cancer cells." (PMID 31511060, 2019). "ACLY also facilitates colon cancer cell metastasis, and high expression levels of ACLY and Catenin β1 (CTNNB1) protein were positively correlated with metastasis of colon cancer." (PMID 33194695, 2020).
colon cancer (continued). "We wonder if ACLY affects the WNT/CTNNB1 signaling pathway, especially CTNNB1, in colon cancer metastasis." (PMID 31511060, 2019). "Increased expression of FASN, ACC, and ACLY, together with significantly increased levels of several types of FAs, thus confirms that de novo synthesis of FAs is upregulated directly in colon cancer epithelial cells, and not just in whole tumors." (PMID 34206240, 2021). "As ACLY could stabilize and interact with CTNNB1, and assisted CTNNB1 translocation through cytoplasm to nucleus, ACLY may promote the CTNNB1 transcriptional activity and the migration and invasion abilities of colon cancer cells." (PMID 31511060, 2019). "In addition, ATP-citrate lyase (ACLY) catalyzes the formation of acetyl coenzyme A from citric acid, which is a precursor of mevalonate acid and fatty acid synthesis through successive condensation reactions and is overexpressed in colon cancer." (PMID 33628242, 2021). "Therefore, we detect the protein levels of ACLY and CTNNB1 in colon cancer pathological tissue." (PMID 31511060, 2019). "ACLY could stabilize CTNNB1 (beta-catenin 1) protein by interacting, and the complex might promote CTNNB1 translocation through cytoplasm to nucleus, subsequently promote the CTNNB1 transcriptional activity and migration and invasion abilities of colon cancer cells." (PMID 31511060, 2019). "However, there is little evidence of ACLY involvement in colon cancer metastasis." (PMID 31511060, 2019).
liver cancer (17 papers, 2016 to 2025). An epithelial or non-epithelial malignant neoplasm that arises from the liver. "The study revealed that sorafenib-resistant liver cancer cells exhibit active lipid metabolism and display elevated expression levels of ACLY." (PMID 40028341, 2025). "Specifically, citrate uptake in liver cancer cells reduced reductive carboxylation by providing citrate to ATP citrate lyase (ACYL)." (PMID 39022761, 2024). "We validated 13C-SpaceM on spatially heterogeneous models using liver cancer cells subjected to either normoxia-hypoxia or ATP citrate lyase depletion." (PMID 39251875, 2024). "We applied this method to interrogate the effect of hypoxia or genetic depletion of ACLY on de novo fatty acid synthesis in murine liver cancer cells, revealing substantial heterogeneity in the contribution of glucose to the cytoplasmic acetyl-CoA pool at the single-cell level." (PMID 39251875, 2024). "ACLY inhibition promotes tumor immunity and suppresses liver cancer, demonstrating that ACLY blockade enhances immunogenicity, a finding that complements our observation that Acly activity links metabolic state to inflammatory gene control and may influence sepsis outcomes." (PMID 41377671, 2025). "For instance, in liver cancer, NAT10 stimulates the acetylation of the ACLY protein’s K468 site, which raises acetyl-CoA synthesis and triggers the transcription of drug-resistant genes, leading to chemotherapy resistance." (PMID 41310903, 2025). "Contrary to SIX1 overexpression, SIX1 KO (knockout) in HepG2 liver cancer cells and SIX1 KD in MHCC97H and SMMC‐7721 liver cancer cells reduced mRNA expression of ACLY, ACC1, FASN, and SCD1, and protein expression of ACLY, FASN, and SCD1." (PMID 39258807, 2024). "Some key enzymes such as ATP-citrate lyase (ACLY), acetyl-CoA carboxylase (ACC), and fatty acid synthesis enzyme (FASN) involved in fatty acid metabolism in cancer cells are upregulated in certain cancers, including liver cancer, and are related to clinical prognosis." (PMID 37394582, 2023). "Interestingly, in 50 pairs of liver cancer and its para-carcinoma tissues, there is significant negative correlation between ERBB4 and ACLY expression, which was consistent with our findings." (PMID 26701850, 2016).
dyslipidemia (14 papers, 2017 to 2025). "Abnormally high expression of ACLY is associated with multiple diseases including cancers, dyslipidemia and atherosclerosis, making ACLY an attractive pharmaceutical target." (PMID 36142671, 2022). "Additionally, considering that FASN and ACLY contribute to hepatic lipogenesis, our results suggest a potential mechanism for the dyslipidemia in adult male mice that is associated with TFA diets." (PMID 29237473, 2017). "ACLY is considered a potential target for various diseases, such as cancer, dyslipidemia, and cardiovascular diseases and thus, the development of ACLY inhibitors becomes important." (PMID 36142671, 2022). "Some of the DE proteins predicted to affect mitochondrial function also cause dyslipidemia, including MECR, CS, ACLY, AOX3, and COX6B1 by RIS, and CYCS, COX6B1, and ENO3 by OLAN." (PMID 33302598, 2020). "Moreover, it takes part in the phosphorylation and activation of the ATP citrate lyase (ACL), which stimulates the formation of lipogenic substrates, elevated fatty acid synthesis, and dyslipidemia, altogether leading to IR development." (PMID 37762992, 2023). "Inhibition of ACLY may be a promising therapeutic approach to dyslipidemia, atherosclerosis and cancer." (PMID 32530819, 2020).
Hypercholesterolemia (14 papers, 2020 to 2025). An increased concentration of cholesterol in the blood. "Recent studies suggest that ACLY is an appealing target in cardiometabolic diseases ranging from hypercholesterolemia to metabolic liver diseases." (PMID 40225566, 2025). "Bempedoic acid, which is a dicarboxylic acid used to treat hypercholesterolemia, is an inhibitor of ACLY that is in the pipeline of MASH treatment." (PMID 39600104, 2024). "This study describes the development of popPK and popPK/PD models to characterize bempedoic acid, an ATP-citrate lyase inhibitor approved for the treatment of hypercholesterolemia." (PMID 37243877, 2023). "Bempedoic acid (BA), an ATP citrate-lyase (ACLY) inhibitor FDA-approved for hypercholesterolemia, catalyzes a key step in fatty acid/sterol synthesis important for cell proliferation." (PMID 36504724, 2022). "On the other hand, ACLY inhibitors have shown effectiveness as cholesterol-lowering drugs in clinical trials of hypercholesterolemia." (PMID 35769513, 2022). "Because the ACLY-mediated conversion of citrate to acetyl CoA is critical for the synthesis of triglycerides and sterols, efforts have been made to develop ACLY inhibitors for the treatment of hypertriglyceridemia and hypercholesterolemia." (PMID 33343508, 2020). "Bempedoic acid (BemA) is an ATP-citrate lyase (ACLY) inhibitor used to treat hypercholesterolemia." (PMID 35884822, 2022). "By inhibiting ACLY, ISOGK treatment thus alleviates hypercholesterolemia and atherosclerosis in mice and hamsters." (PMID 40225566, 2025). "Bempedoic acid is a novel, first-in-class inhibitor of ATP-citrate lyase (ACL), approved for the treatment of hypercholesterolemia." (PMID 36675100, 2023). "A concurrent clinical trial investigated the impact of the ACLY inhibitor ETC-1002 (bempedoic acid) on patients with atherosclerotic cardiovascular disease, heterozygous familial hypercholesterolemia, or both." (PMID 35402505, 2022). "Given the interest in developing ACLY inhibitors to treat many disorders, including hypercholesterolemia and cardiovascular disease, targeting the CSH module of ACLY may provide another viable site for drugging ACLY." (PMID 37076498, 2023). "Bempedoic acid (ETC-1002), an ATP citrate lyase (ACLY) inhibitor that lowers LDL cholesterol, was recently approved by the US FDA for the treatment of heterozygous familial hypercholesterolemia (HeFH) and established atherosclerotic cardiovascular disease (ASCVD)." (PMID 36831004, 2023).
non-small cell lung carcinoma (14 papers, 2010 to 2025). A group of at least three distinct histological types of lung cancer, including non-small cell squamous cell carcinoma, adenocarcinoma, and large cell carcinoma. "In this study, we found that ARHGEF3 was a new regulator of ACLY in non-small cell lung cancer, which stabilized ACLY by reducing its acetylation and decreasing its ubiquitination, thus promoting tumor growth and progression." (PMID 36241648, 2022). "Report only indicates that ACLY expression correlated well with tumor grade, stage and poorer prognosis in non-small cell lung cancer." (PMID 25890184, 2015). "Serine phosphorylation of ACLY in non-small cell lung cancer cell lines has been shown to upregulate ACLY activity and siRNA-mediated KD of the protein induces growth arrest." (PMID 21049007, 2010). "This suggests that ACLY is a promising target for the treatment of non-small cell lung cancer." (PMID 39744129, 2024). "Moreover, it has been observed that ATP citrate lyase (ACL) reverses EMT in non-small-cell lung cancer cell lines by Snai1 repression." (PMID 32793478, 2020). "Similarly, two important enzymes associated with aerobic glycolysis and fatty acid synthesis, malic enzyme (ME) and ATP citrate lyase (ACLY), are highly associated with non-small cell lung cancer (NSCLC) cells." (PMID 30410721, 2018). "Additionally, TINCR can interact with ATP-Citrate Lyase (ACLY), BRAF, and Staphylococcal Nuclease and Tudor Domain Containing 1 (SND1) in nasopharyngeal cancer, non-small cell lung cancer, and post-burn skin fibroblasts, respectively." (PMID 34057016, 2021). "The phosphorylation of ACLY at serine 454 by phosphatidylinositol 3‐kinase (PI3K)/protein kinase B (AKT) pathway is up-regulated with the stage, the tumor differentiation grade, and poor prognosis in non-small cell lung cancer." (PMID 32641978, 2020). "In cancer, Malic enzyme (ME) and ATP-citrate lyase (ACLY) are key enzymes linking aerobic glycolysis and fatty acid synthesis and may therefore be of biological and prognostic significance in non-small cell lung cancer (NSCLC)." (PMID 25962060, 2015).
pancreatic cancer (13 papers, 2020 to 2025). "Here we show that pancreatic cancer-associated fibroblasts (CAFs) regulate tumour cell metabolism through the secretion of acetate, which can be blocked by silencing ATP citrate lyase (ACLY) in CAFs." (PMID 38429478, 2024). "Similarly, another study identified that pancreatic cancer-associated fibroblasts (CAFs) can secrete acetic acid into the stroma of pancreatic cancer, which is mediated by ATP citrate lyase (ACLY)." (PMID 40399304, 2025). "A recent study revealed that the intraperitoneal injection of the ACLY inhibitor SB-204990 in mice attenuated tumorigenicity.Berberine inhibits ACLY-induced lipid metabolism disorders and delays the malignant process of pancreatic cancer." (PMID 39984452, 2025). "Subsequently, multiplex immunofluorescence analysis of pancreatic cancer tissues demonstrated co‐upregulation of ACLY and ACC1 proteins in PSMD14‐high tumor regions." (PMID 41051446, 2025). "We identify a mechanism of ACLY-dependent acetate secretion by stellate cells that orchestrates metabolic and epigenetic reprogramming in pancreatic cancer cells in an ACSS2-dependent manner." (PMID 38429478, 2024). "Moreover, ACLY silencing caused a general shift from de novo synthesis to uptake of palmitate and oleate, consistent with a recent single-cell lipidomics study observing reduced levels of PC species containing saturated and MUFAs upon chemical inhibition of ACLY in pancreatic cancer cells." (PMID 39251875, 2024). "The importance of epigenetic regulation is supported by studies with pancreatic cancer cells where up-regulation of ATP citrate lyase (ACLY), an enzyme that contributes to the synthesis of acetyl-CoA, results in high levels of acetyl-CoA." (PMID 33027921, 2020). "Among FA synthesis inhibitors, BAY ACC022 and SB-204990, respectively targeting the Acetyl-CoA carboxylase (ACC) and ATP citrate lyase (ACLY), reduced tumor growth in pancreatic cancer xenograft models." (PMID 32659999, 2020). "In conclusion, ACLY-mediated secretion of acetate is critical for the growth of pancreatic tumours." (PMID 38429478, 2024). "WB analysis revealed that vitamin C was able to downregulate FASN and ACLY expression in CRL‐2558 and Mia‐PaCa2 human pancreatic cancer cell lines." (PMID 38425123, 2024). "Downregulation of ACLY and FASN through AKT degradation together with CS direct inhibition resulted in an impressive response of gemcitabine in pancreatic cancer tumors." (PMID 38425123, 2024). "Furthermore, we observed increased colocalization of ACLY protein and the CAF marker, smooth muscle actin (αSMA), in primary pancreatic tumours compared to the healthy pancreas." (PMID 38429478, 2024).
atherosclerosis (12 papers, 2012 to 2025). A disease characterized by the build-up of fatty material and calcium deposition in the arterial wall resulting in partial or complete occlusion of the arterial lumen. "Inhibition of the metabolic enzyme ATP-citrate lyase can attenuate atherosclerosis by preventing dyslipidemia and potentially also by reducing macrophage-mediated inflammation." (PMID 33293558, 2020). "Supporting the important role of ACLY inhibition in macrophage function, several reports have pointed ACLY as an important target to mitigate in vivo inflammatory complications, such as exposure to lipopolysaccharide and atherosclerosis." (PMID 38760909, 2024).